CARM1 (coactivator associated arginine methyltransferase 1)
Diseases named in the same sentence as CARM1 in open-access papers (continued):
Sharing a sentence is not in itself a finding about the gene and the disease.
cancer (continued). "Thus, CARM1 promotes cancer by both directly enhancing the activation of the IRE1α/XBP1s pathway and indirectly mediating the silencing of EZH2 target genes." (PMID 34493732, 2021). "Emerging evidence supports an oncogenic function of CARM1 in human cancer." (PMID 34865122, 2021). "Herein, we also added a set of parameters such as gene expression, cancer prognosis, genetic change, immunological infiltration, and the corresponding cellular pathway for investigating CARM1's possible molecular mechanism in the etiology or clinical prognosis of various cancers." (PMID 34745258, 2021). "CARM1-mediated BAF155 methylation promotes cancer cell migration and metastasis." (PMID 34006904, 2021). "Notably, CARM1 amplification/overexpression occurs in ~20% of HGSOCs9, the highest among all cancer types in The Cancer Genome Atlas (TCGA) databases." (PMID 34493732, 2021). "Furthermore, the current study summarized the existing cell- or animal-based data with the correlation between CARM1 and different cancers." (PMID 34745258, 2021). "Emerging reports suggest oncogenic functions of CARM1 in human cancer." (PMID 32487779, 2020). "Among nine members of PRMT family, PRMT5, PRMT1 and CARM1 are most highly expressed in cancer (621 cancer cell lines from cancer cell line encyclopedia database) and such high expression is correlated with worse prognosis of patients in a number of cancer types." (PMID 32743345, 2020). "As CARM1 has not been reported to possess corepressor activity, tumor suppressive YY1 might also utilize coactivator properties of CARM1 to activate tumor suppressor genes to inhibit tumor growth in certain cancer types." (PMID 31217904, 2019). "Thus, despite its oncogenic role, clinically applicable therapeutic strategies based on CARM1 expression in cancer remain to be explored." (PMID 29434212, 2018). "CARM1 is an arginine methyltransferase often overexpressed in human cancer." (PMID 29434212, 2018). "This suggests that epigenetic mechanisms play a key role in CARM1-expressing cancers." (PMID 29434212, 2018). "However, clinically applicable cancer therapeutic strategies based on CARM1 expression remain to be explored." (PMID 29434212, 2018). "According to the Catalogue of Somatic Mutations in Cancer (COSMIC38), frequencies of non-synonymous single nucleotide variants at, and in the proximity of CARM1-regulated ADMA sites (±5 nucleotides), were over twofold higher as compared to the whole human proteome." (PMID 28537268, 2017). "It has also been suggested that CARM1 may impact the balance between oxidative phosphorylation and aerobic glycolysis in cancer cells through methylation of substrates such as PKM219." (PMID 29269946, 2017). "Emerging evidence supports the pathological role of CARM1 in human disease, particularly in cancer." (PMID 28537268, 2017). "Cell-active CARM1 inhibitors are needed to better understand the implications of pharmacological inhibition of CARM1 and to discover and develop novel agents with potential for anti-cancer therapy." (PMID 29269946, 2017). "Furthermore, the two compounds showed good cell permeability and blocked the proliferation of several cancer cells related to CARM1 overexpression." (PMID 27872854, 2016). "In light of the fact that HuR is also an important regulator of cell death, cell differentiation, and human cancer, we postulate that CARM1-HuR regulatory process may impact upon these processes as well." (PMID 23837869, 2013). "Some researchers had investigated the expression of CARM1 in many kinds of malignant tumors." (PMID 23915145, 2013). "CARM1 and p160 family members have been suggested as potential targets in cancer therapy." (PMID 19707557, 2009).
cancer (continued). "Furthermore, we discuss potential CARM1-targeting pharmaceutical interventions for cancer therapy." (PMID 38619752, 2024). "Thus, the use of CARM1 inhibitors to enhance cancer immunotherapies may be of great value in the future." (PMID 37536629, 2023). "Importantly, despite the modest effects on performance by pharmacologically blocking CARM1, our results indicate that investigations into the use of CARM1 inhibition as a treatment for cancer and its related sequelae (e.g., cachectic muscle wasting) should continue." (PMID 37493245, 2023). "Importantly, NFIB is also amplified in ER-negative BC and esophageal squamous cell carcinoma, and targeting CARM1 may attenuate its oncogenic roles in these cancers as well." (PMID 37536629, 2023). "CARM1 is not highly mutated in cancers, but it is often overexpressed." (PMID 37536629, 2023). "Therefore, based on the data from TCGA, CPTAC and other databases, we comprehensively detected the potential significance of CARM1 expression in various cancers from the perspectives of gene expression, gene alteration, immune microenvironment and related signaling pathways." (PMID 35033016, 2022). "However, despite a large body of clinical data, there is currently no pancancer research on the association between CARM1 and other cancer types." (PMID 34745258, 2021). "As a result, CARM1 could be employed as a new anticancer immunotherapy drug target or in combination with other immune checkpoint inhibitors to increase immune responses and infiltration in cancers." (PMID 34745258, 2021). "Originally identified as a co-activator of steroid hormone receptor-mediated transcription, CARM1 has been shown to interact with several nuclear receptors including the estrogen and androgen receptors, and it may mediate oncogenic effects in cancers driven by these pathways." (PMID 29269946, 2017). "In hepatocellular carcinoma cells, CARM1-mediated GAPDH methylation is a key regulatory mechanism of glucose metabolism, retarding the proliferative capacity of cancer cells by regulating the metabolic reprogramming of tumor cells." (PMID 41154773, 2025). "In 2020, a series of cyclic bis(2-bromobenzylidene) analogs were developed as dual inhibitors of CARM1 and CBP/p300, inducing apoptosis in various cancer cell lines, including MCF7, NB4, U937 and SH-SY5Y106." (PMID 41152553, 2025). "Taken together, our study demonstrates that the CARM1-PI3KC2α axis is a key regulator of TTC5-mediated tubulin autoregulation and that disrupting this axis enhances the anti-cancer activity of MTAs." (PMID 40045375, 2025). "This was the first study to identify a gene or pathway regulating CARM1 expression, revealing that CARM1 is regulated by the WDR5‐Myc axis, providing key insights for the treatment of cancers with Myc overexpression." (PMID 39964832, 2025). "In this study, we identified that CARM1 is a potential biomarker in TNBC and upregulated in multiple cancers." (PMID 38476024, 2024). "Thus, CARM1 is upregulated in multiple carcinomas and may be a potential cancer biomarker." (PMID 38476024, 2024). "The functional role of CARM1-mediated GATAD2A methylation in cell cycle gene transcriptional activation and cell cycle progression prompted us to examine its role in cancer." (PMID 38676947, 2024). "Previous results have shown that CARM1 plays a role in modulating the antagonism between EZH2 and BAF155 to facilitate the H3K27me3 deposition by EZ in cancer cells." (PMID 38637528, 2024).
cancer (continued). "CARM1 interacts with and methylates pyruvate kinase M2 isoform (PKM2) to reprogram cancer metabolism from oxidative phosphorylation to aerobic glycolysis in breast cancer cells." (PMID 39266534, 2024). "We observed increased levels of CARM1, NFIB, and NFIBme2a as cancer progresses into malignant disease." (PMID 36690626, 2023). "Herein, we also conducted a correlation analysis between CARM1 and checkpoint genes expression and found that CARM1 expression is highly correlated with CD276 in various cancer types." (PMID 35033016, 2022). "In order to conduct more in-depth research on the pan-cancer relationship between TME and CARM1 expression, ESTIMATE algorithm was used to analyze the relationship between stromal and immune scores and gene expression level among 33 tumors from TCGA." (PMID 35033016, 2022). "Previous studies on arginine methyltransferases in cancers have mostly focused on PRMT1, CARM1, and PRMT5." (PMID 36199122, 2022). "Because tumor infiltrating lymphocytes are independent predictors of sentinel lymph node status and survival in cancer, analogous analysis on potential correlation between CD8+ T cells infiltration and CARM1 expression is also conducted." (PMID 35033016, 2022). "Significantly lower expression of CDKN2AIP and higher level of CARM1 were observed in NTERA-2 and U2OS cell lines, which are all human cancer cells." (PMID 35593475, 2022). "Methylation of MED12 renders cancer cells sensitive to chemotherapy drugs under in vitro and in vivo conditions, and higher levels of MED12 and CARM1 correlate with a better response to chemotherapy drugs." (PMID 34006904, 2021). "Accordingly, of 949 PRMT-related publications, most have focused on cancer, of which 35% studied PRMT5, 28% PRMT1, and 19% CARM1." (PMID 32743345, 2020). "In this study, we aim to elucidate the potential roles of CARM1 and related target genes in NSCLC cancer progression." (PMID 32487779, 2020). "Although the role of CARM1 in different cancers is not clear, studies have confirmed that CARM1 was oncogenic in NSCLC." (PMID 39715739, 2024). "CARM1, a type I PRMTs playing critical roles in cancer progression by methylating histone or nonhistone substrates, was identified as a putative TRIM47-interacting protein." (PMID 39567506, 2024). "CARM1 and OGT expression was higher in cancer tissues than in paracancer tissues." (PMID 39715739, 2024). "Our research has determined the molecular basis of CARM1 carcinogenesis in TNBC and its effective natural inhibitor, which may provide new ideas and drugs for cancer therapy." (PMID 38476024, 2024). "In addition, c-Fos-mediated transcriptional activation is regulated by PRMT4/CARM1, which is involved in cancer and other diseases." (PMID 37564212, 2023). "Thus, there is potential for targeting CBP/p300-altered cancers with CARM1i or a combination of CARM1 and CBP/p300 inhibitors in specific cancers in which residual CBP/p300 expression is required for survival, as in DLBCL." (PMID 37536629, 2023). "Collectively, we successfully identified a novel CARM1/HDAC2 dual-targeting inhibitor and it may play an essential value in the treatment of malignant tumour." (PMID 37528657, 2023). "Furthermore, BAF155 is a substrate for CARM1, and methylation of R1064 in BAF155 results in its redistribution to genes involved in the c-Myc pathway and promotes cancer metastasis in triple-negative breast cancer (TNBC) models." (PMID 37536629, 2023). "Thus, we found that circHMGB2 induces the formation of an immunosuppressive TME via the miR-181a-5p/CARM1 axis, which inhibits the type 1 IFN response in cancer cells and enhances cancer cell resistance to the cytotoxic effects of T cells." (PMID 35525959, 2022). "After literature search, we found there is still a lack of research reports on pan-cancer analysis of CARM1." (PMID 35033016, 2022).
cancer (continued). "Beyond its well-established involvement in the regulation of transcription, recent studies have revealed a novel role of CARM1 in tumorigenesis and development, but there is still a lack of systematic understanding of CARM1 in human cancers." (PMID 35033016, 2022). "There is still no systematic pan-cancer evidence about the relationship between CARM1 and multiple tumor types based on big clinical data." (PMID 35033016, 2022). "The insertion of the 3-bromo-4-hydroxybenzylidene portions at the 3,5 positions of the 1-benzylpiperidin-4-one yielded 2, inactive against PRMT1, SET7, and p300 HAT, and exhibiting selective inhibition of CARM1 and EZH2 (unpublished results), a KMT highly involved in cancer diseases." (PMID 32650558, 2020). "Furthermore PRMTs are well documented to be dysregulated in cancer, with over-expression of PRMT1, CARM1 (PRMT4), and PRMT5 observed in several studies." (PMID 30456387, 2018). "Although an attractive potential target for anti-cancer therapy, there are no reports of suitable CARM1 inhibitors to test the role of its catalytic activity in both in vitro as well as in in vivo tumor xenograft models." (PMID 29269946, 2017). "No deletion was found by sequencing genomic DNA, nor was any mutation identified in CARM1 mRNA derived from MCF7 cancer cells (data not shown), implying that CARM1 in cancer cells is regulated by alternative splicing, resulting in exon 15 exclusion." (PMID 23723242, 2013). "Additionally, UBASH3B, CASP1, CARM1, CHAF1B and PCNT have been studied in other cancers." (PMID 37894336, 2023). "Consequently, the mutational status of CBP/EP300 may be leveraged as a biomarker for predicting the efficacy of small-molecule inhibitors of CARM1 in DLBCL and other cancers." (PMID 37536629, 2023). "Thus, although preclinical studies strongly support the targeting of CARM1 in different cancer settings, no clinical trials can be performed at this stage, which is impeding translational studies in the field." (PMID 37536629, 2023). "Different human cancer cases with altered CARM1 showed the poorer prognosis in progression-free survival (P = 0.013), but not overall survival (P = 0.311), disease-free (P = 0.103), and disease-specific (P = 0.0626) relative to cases without CARM1 variations." (PMID 34745258, 2021). "We could not rule out the possibility of CARM1 expression in both the nucleus and the cytoplasmic portion of cancer cells." (PMID 34745258, 2021). "Indeed, among these targets, transcription of MAP1LC3B and ATG14 genes are directly controlled by this CARM1/TFEB during starvation, a process that could be also involved in cancers when cancer cells are frequently deprived." (PMID 31861179, 2019). "However, the long latency of tumor onset in K5-Carm1 females suggests that overexpression of CARM1 alone is not a major cancer-initiating event but may instead cooperate with an oncogenic insult." (PMID 37536629, 2023). "This indicates that CARM1 inhibitors might work to restore normal gene expression; they will not work to reduce CARM1-enhanced PARylation; and they will prove detrimental when CARM1 levels are used as a marker of vulnerability of cancer cells to EZH2 inhibition." (PMID 37536629, 2023). "We further confirmed that CARM1i phenocopies genetic ablation of CARM1 and NFIB methylation in H69 and CORL47 cells and that inhibitor does not exert an unspecific effect on cancer cells growth." (PMID 36690626, 2023). "Moreover, drugs selectively targeting CARM1-mediated BAF155 methylation may join the family of small molecule inhibitors targeting SWI/SNF complex assembly and function, and are expected to exhibit profound anti-cancer effects, while eliciting even fewer side-effects as compared to CARM1 inhibitors." (PMID 34865122, 2021).
cancer (continued). "Recently, CARM1/PRMT4 and PRMT6 were found to be overexpressed in a variety of human cancers compared to non-neoplastic tissues." (PMID 22916108, 2012). "The results indicate that CARM1 and CHK1 may not be a synthetic lethality to HRAS mutant-driven cancer cells." (PMID 35839996, 2022). "Importantly, this analysis additionally identified a number of instances that are not in the Cancer Gene Census yet, including RXRA and CARM1." (PMID 29572294, 2018).